LINC00113 (long independently transcribed non-coding RNA 113)
Synonyms: SLERCC; C21orf23; NCRNA00113
Gene: Long non-coding RNA gene on chromosome 21 (27,722,327 to 27,751,239, forward strand). Ensembl gene ENSG00000225298.
Diseases named in the same sentence as LINC00113 in open-access papers:
LINC00113 is named in the same sentence as 1 disease in open-access papers, as found by Europe PMC text mining. Sharing a sentence is not in itself a finding about the gene and the disease.
LINC00113 shares sentences with these, for which no sentence is quoted: tumor (1 paper).